MMP9 (matrix metallopeptidase 9)
Diseases named in the same sentence as MMP9 in open-access papers (continued):
Sharing a sentence is not in itself a finding about the gene and the disease.
cancer (continued). "MMP-9 has been demonstrated to play key roles in tumorigenesis participating in the progression of cancer cells to more invasive and metastatic stages." (PMID 24578639, 2014). "It is known that MMP-9 is highly produced and secreted by malignant cells, and that its overexpression correlates with poor prognosis and survival in several cancer types." (PMID 24475095, 2014). "KIOM-C was recently demonstrated to have anti-metastatic activity in highly malignant cancer cells via suppression of NF-κB-mediated MMP-9 activity." (PMID 24878898, 2014). "This is the first report demonstrating the suppression of TPA-stimulated cancer cell invasion by inhibition of MMP-9 expression via suppression of NF-κB pathways in MCF-7 cells." (PMID 24885456, 2014). "MMP-9 is of special interest because its basal expression is normally low, whereas it is highly expressed in most human cancers in response to various growth factors and cytokines." (PMID 24778099, 2014). "It has been reported that the up-regulation of MMP-9 expression contributes to the invasiveness of cancer cells." (PMID 24885456, 2014). "MMP-9 mRNA was detected in mesenchymal cells inside and outside cancer nodules, and in fibrous capsules around the necrosis of cancer nodules." (PMID 24978432, 2014). "In most cancers, MMP-9 is found expressed as pro-MMP-9 which is the inactive zymogen form of the enzyme." (PMID 24713998, 2014). "CD44 and MMP9 have previously been shown to form a complex and together promote invasiveness in cancer cells." (PMID 25184276, 2014). "MMP2 and MMP9 play important roles for cancer metastasis, and IL-17A can affect the expression of MMP2 and MMP9." (PMID 25250801, 2014). "MMP9 is dramatically upregulated in cancer and various inflammatory conditions, and has been proposed as a potential therapeutic target." (PMID 25359725, 2014). "It is therefore essential that specific inhibitors of gelatinase B/MMP-9 proteolytic and non-proteolytic functions are developed in order to determine the potential therapeutic efficacy of inhibiting gelatinase B/MMP-9 function in cancer therapy." (PMID 24473089, 2014). "We and other have also reported that WAVE3-mediated activation of cancer cell invasion and metastasis is in part through its regulation of expression and activity of key MMPs, including MMP9." (PMID 25329315, 2014). "MMP9, known as gelatinase B, promotes the degradation of an important component of the basal membrane, type IV collagen, which is crucial for the invasion of malignant tumors from the proteolysis of ECM with CRC progression and metastasis." (PMID 24737953, 2014). "MMP-9 and VEGF expression are commonly studied in cancer research, and their expression is associated with invasion and metastasis." (PMID 24564183, 2014). "It has been reported that EGFR inhibition efficiently blocked EGF-induced activation of MMP9 and cancer invasiveness." (PMID 25380967, 2014). "We then provide in the present study first evidence of a novel paracrine mechanism that involves the activation of miR-942/MMP-9/VEGF axis in cancer cells to promote endothelial cell migration and resistance to sunitinib." (PMID 24475095, 2014). "Matrix metalloproteinase-9 (MMP-9) is a member of matrix degrading enzymes involved in cancer development, invasion and metastasis." (PMID 25151367, 2014). "The MEK/ERK pathway controls MMP9 expression in various cells, and MMP9 contributes to the invasion, migration, and metastasis of cancer cells." (PMID 24504172, 2014). "With regard to MMP-2 and MMP-9, it is well known that these enzymes promote cancer progression through extracellular matrix and basement membrane degradation, resulting in the exposure of cryptic locations linked to invasion, metastasis and angiogenesis." (PMID 25432084, 2014). "Numerous clinical and experimental studies have demonstrated an increase in particular MMPs, especially MMP-2 and MMP-9 with cancer progression." (PMID 25299052, 2014).
cancer (continued). "We found that 5-nm and 10-nm Au-NPs effectively promoted the expression of ICAM-1and MMP9 in A549 and 95D cells, respectively, which partially explained the enhanced action of the particles on cancer cell invasion." (PMID 24901215, 2014). "In support of this, inhibition of gelatinase B/MMP-9 expression blocks tDC development and increases tDC and Treg numbers in cancer tissues." (PMID 24473089, 2014). "We propose here a graphical abstract illustrating that the Snail-MMP-9 signaling axis maintains several important cancer growth factor receptor signaling platforms in promoting Neu1-MMP-9 crosstalk in complex with these receptors." (PMID 26932374, 2014). "MMP-9 (gelatinase B) is known to play a role in the invasion and metastasis of cancer through degradation of type IV collagen in the basement membrane and by inducing angiogenesis." (PMID 25510449, 2014). "MMP-9 degrades basement membrane and extracellular matrix, which promotes carcinoma cell migration and invasion, thus allowing carcinoma cells to enter the lymphatic system and blood vessels for dissemination and metastatic growth at remote sites." (PMID 24676390, 2014). "We found that AIMs significantly attenuated the cancer cell invasion, which was through the inhibition of MMP-9 expression and EMT." (PMID 23864892, 2013). "MMP9 seems a promising target for preventing angiogenesis, invasion, and metastasis in cancer patients." (PMID 24216994, 2013). "Understanding the different roles of MMP-9 should allow the development of better therapeutic strategies in the treatment of cancer." (PMID 24216994, 2013). "Before the operation, the highest mean concentration of MMP-2 was found in patients with unresectable cancer, whereas the highest level of MMP-9 was in patients with resectable cancer." (PMID 23768069, 2013). "Several other studies also indicated that vanillin can suppress invasion, metastasis, and angiogenesis through decreasing the enzymatic activity and protein expression level of MMP-9 in cancer cell." (PMID 23573143, 2013). "MMP-9 is one of the most important proteins involved in cancer cell metastasis and the status of MMP-9 has been shown to be overexpressed in various cancer cells." (PMID 24179522, 2013). "Here we found the protein activity of MMP-2 and MMP-9, which are involved in degradation of extracellular matrix and play vital roles in cancer cell migration and invasion." (PMID 23764122, 2013). "Gelatinases A (MMP-2) and B (MMP-9) digest gelatins or denatured collagens and are two of the most widely studied MMPs in cancer." (PMID 23696797, 2013). "MMP-2 and MMP-9 are the key enzymes for type IV collagen degradation and are considered to be important for cancer invasion." (PMID 23878609, 2013). "Of these proteases, MMPs such as MMP-2, MMP-9 and the uPA are thought to play a key role in cancer cell invasion and metastasis." (PMID 23874773, 2013). "The prognostic value of MMP-9 in cancer was also investigated, but there were few reports about that of CypA." (PMID 24351116, 2013). "The evidence for MMPs, including MMP-2 and MMP-9, as active contributors to cancer progression arises from animal studies." (PMID 24137425, 2013). "In the evaluation of MMP-9, a significantly higher concentration of this factor was found in the groups with malignant neoplasm, while in the group with benign changes, the concentration of MMP-9 was significantly lower than in the control group." (PMID 23768069, 2013). "Among these MMPs, MMP2 and MMP9 are abundantly expressed, secreted, and activated in various malignant tumors." (PMID 24138815, 2013). "The positive rate of VEGF in cancer was 48.44% (31/64) and the positive rate of MMP-9 was 45.31% (29/64)." (PMID 23418512, 2013). "Because LCK enhances uPA and MMP9 expression resulting in cancer invasion and metastasis, the effect of FOXP3 WT and Y342F mutation on LCK-induced invasion was investigated." (PMID 24155921, 2013).
cancer (continued). "Each MMP was detected at significantly higher rate in urine from cancer patients compared to control subjects except in MMP-9/TIMP-1 and ADAMTS-7." (PMID 23672427, 2013). "To determine the MMP profile in astrocyte CM, we performed gelatin zymography for MMP-2 and MMP-9, well known to correlate with the invasive and metastatic potentials of various cancers." (PMID 24324647, 2013). "Co-expression of NTS and IL-8 positively correlated with increased expression of VEGF and MMP9 in cancer." (PMID 23418512, 2013). "We also assessed the effect of SAHA on MMP-9 activity by gelatin zymography, which is related to the invasive and metastatic properties of cancer cells." (PMID 24130769, 2013). "As the vasculogenic mimicry process is a marker of cancer cell aggressiveness, and as it has been shown to depend on MMP-9 secretion, the effect of Rac3 depletion on vasculogenic mimicry was also tested." (PMID 23388133, 2013). "It is well established that MMP-9 increases in cancer cell lines is a consequence of increased PI3K-Akt activity." (PMID 23840773, 2013). "Particularly, MMP-2 (gelatinase-A) and MMP-9 (gelatinase-B) are highly expressed in epithelial cancer cells and involved in epithelial-mesenchymal transition (EMT) implicated in cancer invasion and metastasis." (PMID 24018886, 2013). "Exogenous Shh increased the expression of the matrix metallopeptidase MMP9, a proteolytic enzyme that plays a key role in cancer progression." (PMID 23667589, 2013). "The involved proteases in migration and invasion, in particular, MMP-2 and MMP-9 were reported to play an important role in cancer invasion and metastasis." (PMID 23431332, 2013). "The predominant SDF-1α receptor is believed to be CXCR4, and signaling through CXCR4 alters the ability of cancer cell lines to adhere to the endothelium and invade through the extracellular matrix components, such as MMP-9, in the bone marrow." (PMID 24094005, 2013). "MMP-9 induces cancer cell invasion by degrading collagen type IV, the most abundant component of the basement membrane." (PMID 23326564, 2013). "MMP-9 is frequently overexpressed in many cancers and correlates with poor prognosis and survival in cancer patients." (PMID 23997800, 2013). "As MMP-2 and MMP-9 are the downstream targets of β-catenin, and play a role in cancer cell metastasis, we also examined the effect of honokiol on the levels of MMP-2 and MMP-9 in NSCLC cell lines." (PMID 23580348, 2013). "MMP-2, MMP-9 and u-PA play important roles in degrading basement membranes and are intricately involved in cancer invasion and metastasis." (PMID 24039823, 2013). "Altered expression of Twist, matrix metalloproteinase (MMP)-2 and MMP-9 proteins has been identified in various types of human cancers." (PMID 23935727, 2013). "The overexpression of MMP-2 and MMP-9 in malignant tumors has been demonstrated to develop a vasculature by angiogenesis." (PMID 24137381, 2013). "The epithelial-mesenchymal transition (EMT), cancer stem cell markers, and cancer metastasis associated proteins such as Snail, Twist, CD133, and matrix metalloproteinase 2 (MMP-2), MMP-9 were differentially expressed in these two cell s." (PMID 23382894, 2013). "The expression and activation of extracellular proteases such as MMP-2 and MMP-9 allow cancer cells to degrade extracellular matrix proteins, thus rendering the migration invasive." (PMID 24023938, 2013). "Some authors reported that the matrix-degrading activity of MMP-9 is nearly 25 times that of MMP-2, and that MMP-9 is more important for the metastatic potential of carcinoma than MMP-2." (PMID 23281640, 2013). "Others have shown that FN and α5β1-integrin signaling via NF-κB induces MMP-9 expression in carcinoma cells." (PMID 23883667, 2013). "It has been found that metalloproteinase MMP-2 is responsible for increased invasiveness while MMP-9 expression in carcinoma cells offers survival advantage." (PMID 24351905, 2013).
cancer (continued). "Together, these data indicate that specific inhibition of MMP-9 expression by DNAzyme has potential as a novel therapeutic modality to decrease the growth and invasion of carcinoma cells in the clinical setting." (PMID 23407024, 2013). "The upregulation of MMP-9 is particularly important for the induction of cancer cell invasion and migration, and suppression of MMP-9 in GBM cells significantly inhibits the invasion, migration and metastatic ability of these cells." (PMID 23183822, 2012). "MMP-9 is a collagenase belonging to the matrix metalloprotease group of proteins which degrade extracellular matrix during cancer cell invasion." (PMID 22952646, 2012). "Cells isogenic with the NSCs and MECs used in this work showing increased secreted MMP-9 activity in the range of 2.0 to 4.5 times control consistently produce malignant tumors upon inoculation into mice." (PMID 22472196, 2012). "4N1K expression appears to be associated with cancer cell progression and survival in UC-UUT patients via the regulation of angiogenesis, apoptosis, and MMP-9 expression." (PMID 22928942, 2012). "Being extracellular proteases, both uPAR and MMP-9 coordinates with other surface receptor to activate intracellular signaling regulating cancer cell progression, invasion, migration and angiogenesis." (PMID 22984561, 2012). "MMP-9 is one of the most important MMPs and is closely related to cancer invasion and metastasis as a result of its strong ECM proteolytic activity." (PMID 23083134, 2012). "On the other hand, a strong MMP-2, MMP-9 or MMP-7 signal in cancer cells has been found to predict better survival." (PMID 22200690, 2012). "In mucosal tissue from inflamed UC, collagen synthesis, pro-MMP-1, TIMP-1, pro-MMP-9 and IL-1β were significantly increased (p<0.03, all comparisons) compared to cancer control tissues." (PMID 23300643, 2012). "Constructive expression of STAT3 can up-regulate the expression of MMP-2 and MMP-9, which are able to efficiently degrade the extracellular matrix and basement membrane, promoting invasion and metastasis of cancer cells." (PMID 22179587, 2012). "Third, both E-selectin and MMP9 have been shown to be involved in cancer-cell invasion and metastasis." (PMID 23190470, 2012). "Among the involved proteases, MMP-2, MMP-9, and u-PA are most vital for the degradation of base membranes, and are therefore deeply involved in cancer invasion and metastasis." (PMID 22363545, 2012). "In the PDAC samples, MMP-9 immunoreactivity was observed in the cytoplasm of cancer cells in 35 of 63 (55.6%) patients." (PMID 22159401, 2012). "MMP-9 is a substantial matrix metalloproteinase that plays an important role in metastasis and cancer invasion, leading to the degradation of matrix components." (PMID 23276144, 2012). "Earlier studies in our lab have demonstrated the role of shRNA specific for MMP-9 (pM) in the induction of G2-M arrest and apoptosis in cancer cells." (PMID 23183822, 2012). "Our findings that LCN2 expression promotes MMP-9 activity are consistent with other cancer cell types." (PMID 23056397, 2012). "For MMP9 (−1562) C/T, heterogeneity was statistically significant in the subgroup analysis based on cancer type and ethnicity of study population under the dominant model." (PMID 22348060, 2012). "Microvessel density (MVD), lymph vessel density (LVD), cancer cell proliferation (PI), apoptotic index (AI), and matrix metalloproteinase (MMP)-9 expression was also determined." (PMID 22928942, 2012). "These last three qualities (increased secretion of MMP-9, invasiveness, and colony formation) are consistent with cancer cells." (PMID 22626610, 2012). "IL-8 levels and MMP-9 activity and levels showed very similar trends, increasing concomitantly and only in patients with established cancer, starting from stage II adenocarcinoma." (PMID 22848630, 2012). "Stronger epithelial MMP-9 expressions have been reported in malignant tumors than in benign or borderline tumors." (PMID 22200690, 2012).
cancer (continued). "MMP-9 was decreased in fibroblast cultures exposed to IL-13, but in tissue extracts there was a general increase in all groups compared to cancer controls." (PMID 23300643, 2012). "Several reports mentioned that blocking the activities of uPAR and MMP-9 resulted in apoptosis in various cancer cells." (PMID 22984561, 2012). "MMP-9 induces cell migration and invasion by degrading collagen in the basement membrane, which allows cancer cells to detach from the ECM and invade surrounding tissues." (PMID 23083134, 2012). "It is well known that ERK1/2 mediates cancer cell metastasis by regulating MMP-9 expression and activity." (PMID 23083134, 2012). "The expression of MMP9 is upregulated in various human cancer types such as esophageal cancer, breast cancer and gastric cancer." (PMID 22348060, 2012). "In the present study, we have shown not only that MMP-9 is overexpressed in cancer tissue, but also that MMP-9 levels are significantly higher in patients with high grade and infiltrative tumors, two very important prognostics factors." (PMID 22695075, 2012). "MMPs are often overexpressed by neoplastic pancreatic epithelium, and MMP-9, an enzyme secreted by cancer cells to digest extracellular matrix and aid invasion and metastasis, was markedly increased in the CCE cells." (PMID 22626610, 2012). "Matrix metalloproteinase-9 (MMP-9) acts as an important oncogene that enhances the invasiveness of cancer cells, and prior research demonstrates that a high level of MMP-9 confers a poor prognosis in a variety of cancers." (PMID 23183822, 2012). "Among the involved proteases, MMP-2, MMP-9, u-PA, and cathepsins reportedly play the most important roles in cancer invasion and metastasis." (PMID 22363545, 2012). "MMP-9 is abundantly expressed in various malignant tumors and is postulated to play a critical role in tumor invasion and angiogenesis." (PMID 22454661, 2012). "Our RT-PCR results (using whole tissue lysates) correlate with the immunohistochemical behavior of MMP-9 in the colonic mucosa, showing a significantly higher expression of MMP-9 in cancer tissue compared to normal colonic mucosa." (PMID 23202950, 2012). "MMP-2 and MMP-9 degrade type IV collagen, and have important roles in the vascular invasion of cancer cells." (PMID 22159401, 2012). "In this study, it was found that luteolin supressed the activation of AKT, ERK, mTOR, P70S6K, MMP-2, and MMP-9 in a concentration-dependent manner in PC-3 cancer cells." (PMID 23300633, 2012). "MMP-2 and MMP-9 are proteolytic enzymes that digest the components of the basement membrane facilitating metastasis of malignant tumors." (PMID 22264292, 2012). "Treatment of both types of cancer cells with IL-5 resulted in significant up-regulation of MMP-9 expression in a concentration- and time-dependent manner, detected using gelatin zymography and immunoblot analysis." (PMID 22962576, 2012). "As expected, MMP expression in normal mucosa was lower than in carcinoma tissue: 2-fold lower for MMP-2 (median carcinomas 10.6 ng mg−1 protein) and 12-fold lower for MMP-9 (median carcinomas 36.7 ng mg−1 protein)." (PMID 22472880, 2012). "In summary, we found that PGE2 rapidly activates JNK1/2 kinase, and then increases the protein levels of uPA and MMP-9, which further promotes cellular motility in human LoVo cancer cells." (PMID 21859479, 2011). "Its effect on protein expression of estrogen recepter alpha(ERα), matrix metalloproteinase 9(MMP-9), cyclinD1, and on cancer cells invasion, proliferation and cell cycle cell in two cell lines were investigated." (PMID 21595884, 2011). "Among them, MMP-9 and MMP-2 have been found to be highly associated with metastatic spread by various cancers." (PMID 21909361, 2011). "17β-Estradiol presents the properties of anti-cancer by downregulating expression of uPA and MMP-9 via deactivation of JNK1/2 in LoVo cells." (PMID 21859479, 2011).